RNPS1 (RNA binding protein with serine rich domain 1)
Description:
Part of pre- and post-splicing multiprotein mRNP complexes. Auxiliary component of the splicing-dependent multiprotein exon junction complex (EJC) deposited at splice junction on mRNAs. The EJC is a dynamic structure consisting of core proteins and several peripheral nuclear and cytoplasmic associated factors that join the complex only transiently either during EJC assembly or during subsequent mRNA metabolism. Component of the ASAP and PSAP complexes which bind RNA in a sequence-independent manner and are proposed to be recruited to the EJC prior to or during the splicing process and to regulate specific excision of introns in specific transcription subsets. The ASAP complex can inhibit RNA processing during in vitro splicing reactions. The ASAP complex promotes apoptosis and is disassembled after induction of apoptosis. Enhances the formation of the ATP-dependent A complex of the spliceosome. Involved in both constitutive splicing and, in association with SRP54 and TRA2B/SFRS10, in distinctive modulation of alternative splicing in a substrate-dependent manner. Involved in the splicing modulation of BCL2L1/Bcl-X (and probably other apoptotic genes); specifically inhibits formation of proapoptotic isoforms such as Bcl-X(S); the activity is different from the established EJC assembly and function. Participates in mRNA 3'-end cleavage. Involved in UPF2-dependent nonsense-mediated decay (NMD) of mRNAs containing premature stop codons. Also mediates increase of mRNA abundance and translational efficiency. Binds spliced mRNA 20-25 nt upstream of exon-exon junctions.
Synonyms: E5.1
Tractability: PROTAC: UniProt records ubiquitination sites on it; ubiquitination databases record sites on it; its protein half-life has been measured.
Gene: Protein-coding gene on chromosome 16 (2,253,116 to 2,268,397, reverse strand). Ensembl gene ENSG00000205937.
Subcellular location: Nucleus; Nucleus speckle; Cytoplasm
Subcellular location (Human Protein Atlas): Nucleoplasm
Pathways (Reactome):
Metabolism of RNA: Nonsense Mediated Decay (NMD) enhanced by the Exon Junction Complex (EJC); Transport of Mature mRNA derived from an Intron-Containing Transcript; mRNA 3'-end processing; mRNA Splicing - Major Pathway
Developmental Biology: Regulation of expression of SLITs and ROBOs
Disease: Dengue Virus-Host Interactions
Gene Ontology:
Molecular function: mRNA 3'-UTR binding; protein binding; RNA binding; nucleic acid binding
Biological process: negative regulation of mRNA splicing, via spliceosome; nuclear-transcribed mRNA catabolic process, nonsense-mediated decay; positive regulation of apoptotic process; regulation of alternative mRNA splicing, via spliceosome; regulation of mRNA processing; DNA-templated transcription; RNA splicing
Cellular component: ASAP complex; cytoplasm; nucleoplasm; nucleus; cytosol; exon-exon junction complex; nuclear speck
Genetic constraint (gnomAD): Loss-of-function variants: 0 observed, 27.75 expected, observed/expected ratio (o/e) 0, 90% interval 0 to 0.11. The upper end of that interval is the gene's LOEUF score, 0.11, which puts it in group 1 of 6, group 1 being the genes least tolerant of losing a copy. Missense variants: 300 observed, 418.56 expected, observed/expected ratio (o/e) 0.72, 90% interval 0.65 to 0.79. Synonymous variants: 147 observed, 141.46 expected, observed/expected ratio (o/e) 1.04, 90% interval 0.91 to 1.19.
Homologues: Orthologues: dog RNPS1 (100% identical), macaque RNPS1 (100% identical), mouse Rnps1 (100% identical), chimpanzee RNPS1 (99% identical), guinea pig RNPS1 (99% identical), rabbit RNPS1 (99% identical), rat Rnps1 (93% identical), rat Rnps1-ps5 (85% identical), pig RNPS1 (82% identical), tropical clawed frog rnps1 (82% identical), zebrafish rnps1 (74% identical), Drosophila melanogaster CG34334 (45% identical), and 1 more.
Diseases named in the same sentence as RNPS1 in open-access papers:
RNPS1 is named in the same sentence as 27 diseases in open-access papers, as found by Europe PMC text mining. Sharing a sentence is not in itself a finding about the gene and the disease. The quoted sentences say what the papers report.
cervical cancer (2 papers, 2019 to 2023). A primary or metastatic malignant neoplasm involving the cervix. "The third isoform switch occurred in RNPS1, which is an essential regulator of the splicing process previously found to be overexpressed in cervical cancer cells." (PMID 37176052, 2023). "Alternative splicing controlled by RNPS1 favors an active Rac1b/RhoA signaling axis, possibly contributing to cervical cancer cell invasion and metastasis." (PMID 37176052, 2023). "Because PVT1 is predicted to interact with 5′-UTR region of RNPS1 mRNA, and is found localized in both nucleus and cytoplasm of cervical cancer cells, this may be one possible mechanism of regulating RNPS1 mRNA translation in cytoplasm." (PMID 30809433, 2019). "We discovered three events in the genes ADAM10, RNPS1, and CLSPN that were previously reported to play a role in the progression or prognosis of cervical cancer." (PMID 37176052, 2023).
colorectal cancer (2 papers, 2020 to 2024). A primary or metastatic malignant neoplasm that affects the colon or rectum. "No direct relation of RNPS1 with colorectal cancer is known, but RNPS1 is essential to nonsense-mediated mRNA decay that plays complex functions in cancer." (PMID 32854705, 2020).
autism (1 paper, 2024). Persistent deficits in social interaction and communication and interaction as well as a markedly restricted repertoire of activity and interest as well as repetitive patterns of behavior. "Pathogenic variants in EEF1B.2 cause autosomal recessive intellectual disability, while rnp-5 ortholog RNPS1 is a risk factor for both intellectual disability and autism." (PMID 39423228, 2024).
bipolar disorder (1 paper, 2011). A disorder of the brain that causes unusual shifts in mood, energy, activity levels and the ability to carry out day-to-day tasks. "The other YWHAZ abnormalities were the interactions with RNPS1 and LGALS1 in schizophrenia; the interactions with MYCBP2, PRDX1 or TP1l in bipolar disorder; the interactions with RPLP2 and VIM in major depression; and the interactions with RPLP0 in both schizophrenia and major depression." (PMID 22373040, 2011).
chronic heart failure (1 paper, 2023). "Since protein phosphorylation can alter the structure and activity of protein, we speculated that hyperphosphorylated Srrm2/Rnps1 might exacerbate post-infarction chronic heart failure through facilitating cargo export from nuclear pore." (PMID 37405054, 2023).
Head-Neck Squamous Cell Carcinoma (1 paper, 2024). "To corroborate these findings, we employed The Cancer Genome Atlas Head-Neck Squamous Cell Carcinoma (TCGA-HNSC) cohort for an assessment of RNPS1 expression and its prognostic significance." (PMID 38246918, 2024).
heart failure (1 paper, 2023). Inability of the heart to pump blood at an adequate rate to meet tissue metabolic requirements. "However, there is no single study on functions and mechanisms of phosphorylation of Srrm2/Rnps1 in heart failure." (PMID 37405054, 2023).
cancer (14 papers, 2012 to 2026). A tumor composed of atypical neoplastic, often pleomorphic cells that invade other tissues. "Indeed, RNPS1 expression exhibited a substantial upregulation in HNSCC samples and was linked to cancer progression." (PMID 38246918, 2024). "Given the interaction between RNPS1 and NAT10 and the existing research indicating NAT10’s impact on tumor occurrence and progression in various cancers, we aimed to investigate whether RNPS1 affects the advancement and metastasis of HNSCC." (PMID 38246918, 2024).
tumor (6 papers, 2017 to 2024). "Our experimental results demonstrate that, compared to the control group, the deficiency of RNPS1 in SCC-15 cells significantly inhibited tumor growth, leading to a marked reduction in tumor volume and weight." (PMID 38246918, 2024). "Our findings demonstrated that depletion of RNPS1 significantly reduced the tumor sphere formation frequency of SCC-9 and SCC-15 cells." (PMID 38246918, 2024). "Lentiviral RNPS1 knockdown weakened tumor cell proliferation and suppressed biomarker expression, reduced the tumor volume, promoted apoptosis in vitro and in vivo, and inhibited UCEC development." (PMID 34817046, 2021). "Knocking down RNPS1 weakened tumor cell proliferation and biomarkers, reduced tumor volume, increased apoptosis in vitro and in vivo, and inhibited UCEC development in our study." (PMID 34817046, 2021). "We found that the tumor volumes of the sh-RNPS1 mice were significantly decreased at 21 and 28 days (p<0.05), and the level of RNPS1 and the proliferation index, Ki-67, were reduced." (PMID 34817046, 2021). "We measured the levels of apoptotic and tumor biomarkers of UCEC to determine their regulation after RNPS1 knockdown." (PMID 34817046, 2021). "The RNPS1 level was significantly higher in tumors than in para-tumor tissues (p<0.05)." (PMID 34817046, 2021). "Additionally, analysis of TCGA database suggests a high expression of RNPS1 in tumor tissues." (PMID 38246918, 2024). "In addition to the factors mentioned, it is likely that other SFs identified here as having consistent changes across all tumor types (SNRPB, RNPS1, RBM34, ELAVL1, and RALYL) could contribute to tumor-associated splicing events in the analyzed datasets." (PMID 33621242, 2021). "We used an RNPS1 knockdown lentivirus (sh-RNPS1) to regulate MMR progression through the Notch signaling pathway and tumor progression in UCEC." (PMID 34817046, 2021).
infection (3 papers, 2008 to 2020). The state of being infected such as from the introduction of a foreign agent such as serum, vaccine, antigenic substance or organism. "These are derived from the number of SRSF1 and RNPS1 sites expressed in either a single A549 cell or a type II primary pneumocyte (cells were not infected; note that infection would be expected to alter the expression profile, which could affect expressed binding site estimates)." (PMID 33299552, 2020).
neurodevelopmental disorder (1 paper, 2022). A behavioral and cognitive disorder with onset during the developmental period that involves impaired or aberrant development of intellectual, motor, or social functions. "For instance, loss-of-function mutations in UPF2, UPF3B, SMG8 and SMG9 genes, and CNVs targeting UPF2, UPF3A, SMG6, EIF4A3, RNPS1 and RBM8A genes, have been implicated in a variety of neurodevelopmental disorders, including DD, ID, ADHD and TAR syndrome." (PMID 35327467, 2022).
neurological disorders (1 paper, 2021). "Moreover, a recent genome-wide CRISPR-Cas9 screen has identified two additional factors, SRSF11 and RNPS1, that contribute to SRRM4-dependent microexon regulation, and these genes have also been implicated in ASD and other neurological disorders." (PMID 33482885, 2021).
RNPS1 also shares sentences with these, for which no sentence is quoted: HIV-1 infection (3 papers); breast carcinoma (2); acute myeloid leukemia (1); autosomal recessive intellectual disability (1); breast tumors (1); glioblastoma (1); influenza (1); Intellectual disability (1); leukemia (1); major depression (1); malaria (1); myelodysplastic syndrome (1); schizophrenia (1); uterine corpus endometrial carcinoma (1); viral infection (1).